NOS1 (nitric oxide synthase 1)
Diseases named in the same sentence as NOS1 in open-access papers (continued):
Sharing a sentence is not in itself a finding about the gene and the disease.
NOS1 also shares sentences with these, for which no sentence is quoted: Cerebral ischemia (43 papers); ischemia (38); heart failure (15); colitis (13); type 2 diabetes (13); cardiovascular diseases (9); myopathies (9); metabolic syndrome (8); type 1 diabetes (7); Crohn disease (6); gastroparesis (6); neuropathy (6); mood disorder (5); ulcerative colitis (5); bipolar disorder (4); injury (4); muscle atrophy (4); myopia (4); anemia (3); Arthritis (3); Atrophy (3); Becker muscular dystrophy (3); brain injury (3); cerebral malaria (3); chronic heart failure (3); chronic obstructive pulmonary disease (3); cystic fibrosis (3); diabetic retinopathy (3); dilated cardiomyopathy (3); essential hypertension (3).
A further 200 diseases each share a sentence with NOS1 in 3 papers or fewer.